IGF1 (insulin like growth factor 1)
Diseases named in the same sentence as IGF1 in open-access papers (continued):
Sharing a sentence is not in itself a finding about the gene and the disease.
Insulin resistance (continued). "In addition, low IGFBP-1 and IGFBP-2 coupled with elevated IGF-1, may represent compensatory mechanisms in response to increasing insulin resistance." (PMID 29351335, 2018). "However, metformin therapy decreases levels of IGF-1, improves insulin resistance in peripheral tissues, and alleviates the circulating insulin levels, which, in turn, may result in reduced risk of cancer." (PMID 27903961, 2017). "Indeed, insulin resistance, elevated insulin-like growth factor (IGF)-1, and AGEs are all related to body fat distribution and adipocyte biology, which might partially explain the gender difference found in our study." (PMID 28212675, 2017). "For example, dysregulation of insulin-IGF-1 axis, sex hormones, or adipokines in obese individuals might result in multiple systemic metabolic alterations, such as insulin resistance, hyperglycemia, and chronic inflammation that can contribute to increased cancer risk in such patients." (PMID 28678173, 2017). "However, increase of the insulin growth factor-1 (IGF-1) level, especially within the first months of treatment, may temporary improve insulin sensitivity, even in patients with pre-existing insulin resistance." (PMID 28397183, 2017). "Thus, measurements of body composition and IGF-1 levels can predict insulin resistance." (PMID 28654680, 2017). "Thus, TRPV1 agonists such as capsaicin may prevent brain insulin resistance by the activation of insulin/IGF-1 signaling." (PMID 25755673, 2015). "Besides peripheral insulin resistance, this alteration may be present in the brain accompanied by IGF1 resistance, and IRS-1 and IRS-2 dysfunction, potentially triggered by Aβ oligomers and cognitive decline." (PMID 25346723, 2014). "Insulin resistance, hyperinsulinaemia (either endogenous due to insulin resistance or exogenous due to administered insulin or insulin secretagogues) and elevated levels of IGF-1 reduce apoptosis and increase cell proliferation in target cells, leading to tumour development 36–79." (PMID 23668396, 2014). "Insulin resistance and hyperinsulinemia could result in increasing of IGF-1." (PMID 25157753, 2014). "Indeed, in contrast to liver, muscle and adipose tissue where diabetes-induced increase in plasma insulin is compensated by diabetic insulin resistance, insulin-sensitive cancer cells in the diabetes context are exposed to high insulin and IGF-1 acting as growth factors." (PMID 25375205, 2014). "As such, a larger proportion of patients are more likely to be on appropriate DM therapy, which typically includes metformin as a front line agent, and may abrogate the potential adverse effect of insulin resistance or IGF-1 on survival and account for our improved survival findings." (PMID 24879130, 2014). "The AMPK activating effects of PS may improve insulin resistance, thereby reducing IGF-1 levels." (PMID 23434903, 2013). "In addition to insulin, insulin-like growth factor-1 (IGF-1) is another substance that lowers serum levels of glucose in both rats and humans and has even the capability of doing so in patients with severe insulin resistance." (PMID 20414467, 2010). "Treatment with glucocorticoids can be associated with IGF-1 resistance, similar to insulin resistance, which may explain the negative correlation in the P-group." (PMID 18986531, 2008). "We observed a strong inverse correlation between IGF-1 and TNF-α, a key pro-inflammatory cytokine known to drive insulin resistance." (PMID 41393761, 2025). "The essential point in the connection of insulin resistance (as an outcome of PCOS) and acne is that overproduction of insulin leads to increasing levels of insulin-like growth factor 1 (IGF-1)." (PMID 41473651, 2025). "Compensatory hyperinsulinemia from insulin resistance reduces hepatic IGF binding protein production, increasing bioavailable IGF-1 that stimulates IGF-1R signaling pathways promoting cellular growth and metastatic spread." (PMID 41561157, 2025).
Insulin resistance (continued). "During puberty, there is a surge in growth hormone (GH) and insulin-like growth factor-I (IGF-1), which increases insulin resistance, leading to increased lipid breakdown and increased free fatty acids (FFAs) in the circulation." (PMID 40019178, 2025). "Modulation of this pathway can be monitored through measurement of fasting serum insulin, IGF-1, and IGFBP-3 levels, as well as by evaluating insulin resistance indices, such as the homeostatic model assessment for insulin resistance (HOMA-IR)." (PMID 41008741, 2025). "There are data that confirm the impact of conditions such as insulin resistance, chronic inflammation, cirrhosis, or arteriosclerosis on the increased production of MSTN antagonists such as irisin, follistatin, or IGF-1." (PMID 38542721, 2024). "Another potential mechanism for the increased BMD in diabetic patients relates to elevated levels of insulin and insulin-like growth factor-1 (IGF-1), particularly during the early stages of diabetes or in cases characterized by insulin resistance." (PMID 39741509, 2024). "It is important to note that the stimulation of GSK3β leads to phosphorylation of insulin receptor substrate protein 1 (IRS1) affecting insulin like growth factor 1 signaling (IGF-1) and resulting in downstream insulin resistance." (PMID 39416952, 2024). "This study assessed the serum concentrations of total Insulin-Like Growth Factor-1 (IGF-1) in patients with Type 2 Diabetes Mellitus (T2DM) and examined its relationship with insulin resistance." (PMID 39578883, 2024). "This suggests that IL-6, IGF-1, and VEGF are important inflammatory factors promoting insulin resistance, and glucose fluctuations in diabetic cataracts and these factors are closely related to oxidative stress injury." (PMID 39015537, 2024). "Peripherally, IGF-1 increases glucose uptake and functional inactivation of IGF1R in skeletal muscles of mice, resulting in insulin resistance and diabetes." (PMID 37654561, 2023). "The animals exhibited higher insulin levels, insulin resistance (indicated by increased HOMA-IR), lower IGF-1 levels, and increased IGF-1R phosphorylation." (PMID 37569816, 2023). "Other targets of this miRNA are the genes Insulin Receptor Substrate 1 and 2 (IRS1/IRS2) and Insulin-Like Growth Factor 1 (IGF-1), which are closely related to insulin resistance, a characteristic condition of diabetes." (PMID 37511739, 2023). "However, increased IGF‐1 in CAFQ may be related to insulin resistance induced by cafeteria diet." (PMID 37970433, 2023). "Insulin resistance, one of the hallmarks of NAFLD, increases the secretion of insulin and insulin-like growth factor (IGF)-1." (PMID 36831649, 2023). "Among these pathways, PPARGC1A, CD36, IRS2, PCK2, and IGF1 were enriched in the AMPK signaling pathway, and PCK2 was additionally enriched in the adipocytokine signaling pathway and insulin resistance." (PMID 37958518, 2023). "IGF-1 levels increase as insulin resistance develops; with worsening of insulin resistance, the IGF-1 concentration reaches a plateau level, and subsequently, when glucose levels reach concentrations typical of type 2 diabetes, IGF-1 levels tend to decline." (PMID 37438734, 2023). "Given the similarities between insulin and insulin-like growth factor 1 (IGF-1) receptors, recombinant human IGF-1 (rhIGF-1) has been used to treat severe insulin resistance including DS." (PMID 36337021, 2022). "This happens, at least in part, because of reduced insulin-like growth factor-1 (IGF-1) levels and the development of insulin resistance." (PMID 35053505, 2022). "It was found that the serum IGF1 level and insulin resistance index (HOMA-IR) of patients with PCOS were significantly increased, and IGF1 was positively correlated with HOMA-IR." (PMID 36742000, 2022). "Also, age-related insulin resistance may profoundly affect the effects IGF-1 in aged individuals." (PMID 35869380, 2022).
Insulin resistance (continued). "Studies suggest that the circulating level of the anabolic factor insulin-like growth factor-1 (IGF-1) is decreased, and insulin resistance occurs in the cancer cachexia model." (PMID 35388147, 2022). "Due to the existence of insulin resistance in T2DM, IGF-1 and insulin are at a high level over a long period of time, with secondary elevation in IGF-1R." (PMID 35035440, 2022). "An additional protein with less binding for IGF1, called IGFBP1 or IGFBP-7, has recently emerged as a marker of insulin resistance and MAFLD." (PMID 36557260, 2022). "Consistent with this, patients with IGF-1 gene deletion exhibit severe insulin resistance, and mice with IGF-1 deletion in the liver exhibit insulin resistance and administration of IGF-1 improved the insulin-resistant state." (PMID 35745205, 2022). "IGF-1 levels are related to beta cell function and growth in the first year, and at age three, IGF-1 is related to BMI and insulin resistance." (PMID 36714657, 2022). "Collectively, our data suggest that MKP-2 promotes IGF-1, SDF-1, FKN, and IL-10 signaling to contribute to development of insulin resistance, NAFLD, fibrosis, and inflammation." (PMID 35745205, 2022). "Sleep deprivation can directly alter the transcription and post-transcriptional translation levels of IGF-1 mRNA in vivo, thereby lowering IGF-1 concentrations below the normal range and exacerbating insulin resistance." (PMID 36120463, 2022). "The levels of insulin and insulin resistance are influenced by the accumulation of WAT, and the levels of insulin can affect the secretion of insulin-like growth factor-1 (IGF-1)." (PMID 35215391, 2022). "In the current study, we focused on SNPs of three genes (JAZF1, IGF1, and IGF2BP2) which have been shown to affect lipid metabolism and insulin resistance." (PMID 33390804, 2021). "Some studies even correlate Homeostasis Model Assessment of Insulin Resistance (HOMA) index and higher IGF1 levels during childhood." (PMID 34447729, 2021). "IGF-1, IGF-1 receptor and insulin receptors has been found in thyroid carcinoma, hyperinsulinemia and insulin resistance were also found to play a role of carcinogenesis." (PMID 34550096, 2021). "Five SNPs in three genes (rs864745 in JAZF1, rs35767 in IGF1, and rs4376068, rs4402960, and rs6769511 in IGF2BP2) that contribute to insulin resistance involving lipid metabolism were genotyped using the MassArray method in a Chinese population." (PMID 33390804, 2021). "As a major signaling adapter of the insulin/IGF-1 signaling pathway, IRS-1 stimulates a variety of downstream pathways to participate in the regulation of insulin resistance and cell differentiation." (PMID 34295306, 2021). "Five SNPs in three genes (rs864745 in JAZF1, rs35767 in IGF1, and rs4376068, rs4402960, and rs6769511 in IGF2BP2) contributing to insulin resistance involving lipid metabolism were genotyped." (PMID 33390804, 2021). "In addition, IGF1R blockade might also determine the dysregulation of IGF1R/IGF1/GH, which might determine the inhibition of IGF1 hypoglycemic effect and/or a compensatory increase in circulating GH, leading to increased liver glucogenesis and insulin resistance." (PMID 34440844, 2021). "Comparison of insulin resistance, glucose (FBG, FINS, and HbA1c) and bone metabolism (Ca, P, calcium, and phosphorus production, iPTH, BALP, and IGF-1) indexes between male and female." (PMID 35223754, 2021). "Our study found that reduced IGF-1 were present in obese prepubertal boys with lower values of WBISI, which is a surrogate marker of insulin resistance." (PMID 34485526, 2021). "MiR-320 was found to regulate IGF-1 and IGF1R69 expression, playing a key role in developing insulin resistance in adipose tissues and endothelial cells." (PMID 32178730, 2020). "There was a favorable effect of increasing the IGF-1 level on waist circumference compared to decreasing the IGF-1 level (p=0.05), but a detrimental effect on insulin resistance (p=0.03)." (PMID 33633687, 2020).
Insulin resistance (continued). "On the other hand, due to an increase of the IGF-1/IGFBP-3 ratio, this stimulates the predominance of high mTOR-dependent metabolic activity and insulin resistance." (PMID 33333870, 2020). "The insulin resistance seen in NAFLD, diabetes and obesity results in compensatory systemic hyperinsulinaemia and increased Insulin-like Growth Factor-1 (IGF-1) production in the liver." (PMID 30819129, 2019). "Further, the degree of insulin resistance (HOMA-IR) correlated with GH (r = 0.76, p = 0.03) and IGF-1 (r = 0.72, p = 0.03)." (PMID 30948746, 2019). "A previous study had shown that these mice have normal body growth and serum IGF-1 levels, although brain-specific STAT5-knockout mice exhibit late onset obesity and insulin resistance." (PMID 31939479, 2019). "Anthropometric measurements, body composition and biochemical profile were determined along with Growth Hormone (GH)/Insulin like Growth Factor 1 (IGF-1) axis and insulin resistance (homeostatic model assessment for insulin resistance—HoMA-IR)." (PMID 31527400, 2019). "The patient had a low circulating IGF-1 concentration, extremely low IGFBP-3 concentration, insulin resistance and osteopenia." (PMID 30717585, 2019). "Thus, it seems plausible that increasing IGF‐1 in the brain may represent an important therapeutic alternative to circumvent central insulin resistance for the treatment of these diseases in older humans, a possibility that should be considered in future clinical trials." (PMID 26534869, 2016). "Considering that IGF-1 regulates IGFBP-1 and IGFBP-2, it is reasonable to conclude that early changes in insulin resistance alter their concentrations." (PMID 26733412, 2016). "The exogenous administration of IGF-1, at low doses (similar to those used in the present work), restored IGF-1 serum levels reducing dyslipidemia and insulin resistance, oxidative liver damage and mitochondrial dysfunction." (PMID 26467524, 2015). "It should be noted that in obese patients with weak insulin resistance the free IGF-1 level increased insignificantly due to the lowered IGFBP1 level, while total IGF-1 level was maintained." (PMID 28031898, 2015). "In animal models, mice become insulin resistant when liver synthesis of IGF-1 is deleted, and IGF-1 administration corrects this insulin resistance." (PMID 24586785, 2014). "JNK activation is proposed to promote insulin resistance through upregulation of IRS serine phosphorylation, and IRS is a key common signaling component of both the insulin and IGF-1 pathways." (PMID 24252636, 2013). "We then analyzed the correlations between serum IGFBP-7 protein levels and other laboratory variables, including fasting glucose, fasting insulin, homeostasis model of assessment insulin resistance (HOMA-IR), IGF-1, and IGFBP-1." (PMID 24180466, 2013). "Their serum fasting insulin, fasting glucose, insulin-like growth factor-1, adiponectin, IGFBP-1, triglyceride concentrations, and the homeostasis assessment model for insulin resistance (HOMA-IR) were evaluated." (PMID 23186039, 2012). "Recent studies have demonstrated that lower baseline IGF1 levels predict the subsequent development of impaired glucose tolerance (IGT), type 2 diabetes, cardiovascular disease and a worsening state of insulin-resistance." (PMID 20108502, 2008). "Insulin resistance, a core metabolic derangement in PCOS, further contributes to acne by suppressing hepatic SHBG synthesis, thereby increasing free testosterone, and by amplifying IGF-1, mediating follicular inflammation." (PMID 40868844, 2025). "Testicular spermatogenesis may be impacted by insulin resistance-induced changes in the insulin-like growth factor (IGF) system, including a reduction in IGF-1 levels." (PMID 41153443, 2025). "Furthermore, dysregulation of IGF-1 signaling emerged as a central mechanism, with decreased circulating IGF-1 levels and impaired cardiac IGF-1 signaling contributing to obesity, insulin resistance, and systemic metabolic syndrome." (PMID 40282189, 2025).
Insulin resistance (continued). "Obesity exacerbates testosterone deficiency in men and may induce insulin resistance; elevated insulin and insulin-like growth factor 1 (IGF-1) initially facilitate fat accumulation, but prolonged insulin resistance adversely affects muscle protein metabolism." (PMID 40718355, 2025). "On the other hand, insulin resistance induced by the excess of IGF-1 decreases NO production and thus increases microvascular wall hypertrophy and microvascular dysfunction that correlate with IGF-1 levels." (PMID 37306894, 2024). "Insulin resistance can lead to hyperinsulinemia, which can directly activate insulin-like growth factor-1 (IGF-1) receptor, or inhibit IGF-binding protein (IGFBP) to increase the bioavailability of IGF-1 to the IGF-1 receptor." (PMID 39509387, 2024). "In addition, during cachexia, both patients with cancer and mouse models show reduced circulating levels of the anabolic factor insulin-like growth factor-1 (IGF-1), alongside the development of insulin resistance." (PMID 39519503, 2024). "Insulin resistance, hyperinsulinemia, type 2 diabetes, and polycystic ovarian syndrome (PCOS) are known to promote endometrial proliferation by reducing the levels of sex hormone binding globulin and insulin-like growth factor 1 (IGF-1) binding proteins." (PMID 39336931, 2024). "These include hyperinsulinemia (due to insulin resistance in T2DM or use of exogenous insulin) and increased levels of IGF-1 which stimulates cell proliferation and inhibits apoptosis, and hyperglycemia affecting intracellular metabolism and impairing the immune system." (PMID 38492115, 2024). "Our findings indicate that insulin resistance has negative effects on childhood and adult adiposity, while IGF-1 resistance has negative effects on childhood adiposity." (PMID 39174749, 2024). "Insulin resistance and hyperglycemia stimulate IGF-1 signaling, and IGF-1 then activates oncogenic signaling pathways such as PI3K/Akt/mTOR, JNK/MAPK, Wnt, and Ras/MEK/ERK, which promote cell proliferation and angiogenesis and inhibit apoptosis, eventually fostering the development of HCC." (PMID 39123380, 2024). "Using a biologically informed approach, our findings indicate negative effects of insulin resistance on childhood and adult adiposity, as well as negative effects of IGF-1 resistance on childhood adiposity." (PMID 39174749, 2024). "CKD is not only a state of suppressed IGF1/PI3K/Akt signaling, but also of insulin resistance, which might be based on reduced expression or inactivation of IR/IGF1R on target cells." (PMID 38791164, 2024). "Their association with cancer may be partly related to elevated levels of insulin-like growth factor-1 (IGF-I) and hyperinsulinemia secondary to insulin resistance." (PMID 39769097, 2024). "Notably, T2DM patients with a high Insulin Resistance (IR) index, as measured by the Homeostatic Model Assessment for Insulin Resistance (HOMA-IR), exhibited lower IGF-1 levels compared to those with normal IR." (PMID 39578883, 2024). "Liver specific deletion of IGF1 leads to elevated levels of growth hormone and this is presumed to contribute to the insulin resistance but not elevated blood glucose they experience." (PMID 37713040, 2023). "Our main findings showed that IGF-1 levels correlated differently with metabolic and insulin resistance-related variables in subjects with or without MetS." (PMID 37106164, 2023). "Insulin resistance may increase serum insulin levels in T2DM and, by blocking IGF-binding proteins, indirectly increase IGF-1 biological activity." (PMID 36890832, 2023). "Diet change and weight loss are less important in the case of patients with acromegaly because they generally do not have visceral obesity, and insulin resistance is influenced by excess GH and IGF-1." (PMID 37628857, 2023).